SLC4A1 (solute carrier family 4 member 1 (Diego blood group))
Diseases named in the same sentence as SLC4A1 in open-access papers (continued):
Sharing a sentence is not in itself a finding about the gene and the disease.
haemolytic anaemia (3 papers, 2011 to 2026). "The biallelic SLC4A1: p.Ala858Asp variant was characteristically associated with increased osmotic fragility of red blood cells, manifesting as haemolytic anaemia." (PMID 41134021, 2026). "We report an extremely rare case of HS in China that presented with hereditary hemolytic anemia with band 3 deletion resulting from a novel variant of SLC4A1, and systematically review a large number of related literatures." (PMID 36463227, 2022).
Hypertension (3 papers, 2013 to 2025). The presence of chronic increased pressure in the systemic arterial system. "SLC4A1 has been associated in GWAS with hypertension and its expression in the kidney is altered in animal models with altered sodium absorption." (PMID 28178938, 2017).
nephrocalcinosis (3 papers, 2019 to 2025). Nephrocalcinosis is a disorder that occurs when too much calcium is deposited in the kidneys. "For example, mutations in six of the amelogenesis imperfecta-associated genes (CLDN16, CLDN19, FAM20A, KCNJ1, SLC4A1, and WDR72) are associated with nephrocalcinosis, hypercalciuria, and renal failure." (PMID 33672174, 2021).
nephrolithiasis (3 papers, 2019 to 2026). The presence of a calculus in the pelvis of the kidney; this is most often composed of mineral salts and proteins. "For example, for nephrolithiasis (PanelApp panel 149), SLC9A3, SLC4A1, and SLC6A19 appear on the top of the gene list." (PMID 35456490, 2022).
osteosarcoma (3 papers, 2008 to 2024). A usually aggressive malignant bone-forming mesenchymal neoplasm, predominantly affecting adolescents and young adults. "IFITM5, MMP13, PANX3, and MAGEA6 were some of the most overexpressed genes in osteosarcoma samples, while SLC4A1, HBA1, HBB, AQP7 genes were some of the top downregulated genes." (PMID 38966281, 2024). "SLC4A1, solute carrier family 4 member 1, was found to be among the highly significant differentially expressed genes in osteosarcoma." (PMID 37681913, 2023). "Among the DEPs identifying oseoblastic and telangiectatic osteosarcoma subtypes are CAT, FGA, SLC4A1, and ACTA2." (PMID 37681913, 2023).
ovarian carcinoma (3 papers, 2010 to 2025). A malignant neoplasm originating from the surface ovarian epithelium. "Limited studies have investigated SLC4A1 expression and its functional role in ovarian cancer." (PMID 40565351, 2025). "Further studies are warranted to investigate the role of SLC4A1 in ovarian cancer." (PMID 40565351, 2025). "We validated the expression of proteins of interest (COL12A1, FUBP1, PLEC, SLC4A1, and TKT) using immunohistochemistry (IHC) and further characterized their expression in online ovarian cancer databases." (PMID 40565351, 2025). "By analyzing ovarian cancer datasets with the cBioPortal, we found the highest frequency of AE2 (SLC4A2) gene amplification (TCGA Provisional, 10.0%; TCGA 2011, 4.4%), as compared to AE1 (SLC4A1) (TCGA Provisional, 0.3%; TCGA 2011, 0.3%) and AE3 (SLC4A3) (TCGA Provisional, 2.6%; TCGA 2011, 0.6%)." (PMID 28743911, 2017).
autoimmune disease (2 papers, 2017 to 2022). A disorder resulting from loss of function or tissue destruction of an organ or multiple organs, arising from humoral or cellular immune responses of the individual to their own tissue constituents. "In patients with overt dRTA, etiologic screening was profitable, with a genetic cause being identified in 42.9% of cases (N = 3) without autoimmune disease (N = 7), all having the same missense mutation in Arg589 of the SLC4A1 gene, common in Europe." (PMID 28542241, 2017).
glioma (2 papers, 2023 to 2024). A benign or malignant brain and spinal cord tumor that arises from glial cells (astrocytes, oligodendrocytes, ependymal cells). "Out of these NRGs, 19 NRGs (EGLN3, HILPDA, HMBS, HYOU1, BNIP3, etc.)were found to be enriched in glioma tissues while 13 genes (SLC4A1, IL6, EPAS1, ACE, HMOX1, etc.)were decreased compared to normal tissues." (PMID 37934582, 2023).
kidney damage (2 papers, 2024). "We confirmed the influence of several known NEMG on kidney disease and function and found novel associations for SLC39A13, CFL1, ACP2 or ATP5G1 with serum variables and kidney damage, and for SLC4A1, NUP210 and MYH14 with ESKD." (PMID 38858654, 2024).
mesothelioma (2 papers, 2022). A usually malignant and aggressive neoplasm of the mesothelium which is often associated with exposure to asbestos. "Furthermore, since especially mesothelioma is associatedwith asbestos exposure, expression arrays of a larger panel of mesotheliomacell lines (n = 33) were analyzed and SLC4A1 andSLC26A1 expression compared to nonmalignant mesothelial (n = 2) cells." (PMID 36410050, 2022).
Parkinson’s (2 papers, 2023 to 2024). "On the other hand, SLC4A1 has been associated with Parkinson’s disease and Lewy body dementia." (PMID 39146369, 2024).
rickets (2 papers, 2016 to 2021). Bone softening and weakening usually caused by deficiency or impaired metabolism of vitamin D. Deficiency of calcium, magnesium, or phosphorus may also cause rickets. "Seven of the amelogenesis imperfecta-associated genes (CYP27B1, EPNN1, PHEX, SLC4A1, SLC4A4, VDR, and WDR72) are known to cause rickets when mutated." (PMID 33672174, 2021).
Stroke (2 papers, 2020). Sudden impairment of blood flow to a part of the brain due to occlusion or rupture of an artery to the brain. "In male patients, four of the 34 SVD-associated genes were unique to that specific stroke cause: CYP4F2, GP1BA, solute carrier family four, member one (SLC4A1), and F13A1, which was also uniquely expressed in the male cohort." (PMID 33193047, 2020). "In female patients, 12 of the 34 SVD-associated genes were unique to that stroke cause, including FGA, SLC22A3, both unique to the female cohort, and SLC4A1 which was also expressed in males, though by different exons and junctions." (PMID 33193047, 2020). "For the extreme contrast of “stroke” versus “long survivor”, only four gene sets – SERPINC1, SLC22A5, CACNA1H, and SLC4A1 [MIM: 109270] – were significant." (PMID 32898326, 2020).
thalassaemias (2 papers, 2016 to 2024). "In our study, we found overexpression of the genes SLC4A1, ANK1, EPB41, EPB42, SPTA1, SPTB, and STOM, all of which are involved in maintaining erythrocyte structure and function, in patients with thalassemia and SCD." (PMID 39519257, 2024).
adenoma (1 paper, 2021). A neoplasm arising from the epithelium. "One functional group of transporters to be discussed are Cl−/HCO3− exchangers belonging to the class of SLC (solute carrier) 4 proteins such as AE1 (SLC4A1), AE2 (SLC4A2), and AE3 (SLC4A3), or SLC26 proteins such as DRA (SLC26A3; downregulated in adenoma)." (PMID 33914143, 2021).
asthma (1 paper, 2022). "It is found that the AUC values of SERPINB2, SLC4A1, TAAR9 in patients with asthma and normal people are 0.854, 0.819 and 0.688, respectively." (PMID 35967302, 2022). "PCR analysis of SERPINB2, SLC4A1, and TAAR9 genes, which also exist in the mouse model of asthma, was conducted to verify the accuracy of the results." (PMID 35967302, 2022). "The findings showed that the level of SERPINB2 mRNA in the model of asthma is downregulated while that of SLC4A1 mRNA and TAAR9mRNA is upregulated compared with those of normal mice." (PMID 35967302, 2022).
autosomal recessive distal renal tubular acidosis (1 paper, 2022). The autosomal recessive form of distal renal tubular acidosis (dRTA) characterized by hypokalemic hyperchloremic metabolic acidosis. "Mutations in solute carrier family 4 member 1 (SLC4A1) encoding anion exchanger 1 (AE1) are the most common cause of autosomal recessive distal renal tubular acidosis (AR dRTA) in Southeast Asians." (PMID 36320073, 2022).
blood disease (1 paper, 2021). A disease that occurs in the blood. "Consequently, our results discussed the connections between the hub genes EPB42, CALR, SLC4A1, MPL and PMF together with other related blood diseases comprehensively." (PMID 34633991, 2021).
colorectal cancer (1 paper, 2025). A primary or metastatic malignant neoplasm that affects the colon or rectum. "However, increased SLC4A1 cytoplasm expression was observed in gastric and colorectal cancers." (PMID 40565351, 2025).
deafness (1 paper, 2022). An inherited or acquired condition characterized by the complete loss of the ability to hear from one or both ears. "Patients with SLC4A1 gene variation can inherit in an AD/AR manner, with or without deafness." (PMID 35612621, 2022).
endolymphatic hydrops (1 paper, 2022). An accumulation of endolymph in the inner ear (labyrinth) leading to buildup of pressure and distortion of intralabyrinthine structures, such as cochlea and semicircular canals. "SLC4A1 protein expression levels have been observed to decline in an experimental endolymphatic hydrops model of MD; thus, SLC4A1 is considered protective against MD." (PMID 35741759, 2022).
endothelial dysfunction (1 paper, 2025). In vascular diseases, endothelial dysfunction is a systemic pathological state of the endothelium (the inner lining of blood vessels) and can be broadly defined as an imbalance between vasodilating and vasoconstricting substances produced by (or acting on) the endothelium. "The set includes genes such as CLDN18, NOS2, SLC4A1, CA4, COL17A1, and SP7, many of which have been implicated in vascular inflammation, endothelial dysfunction, and extracellular matrix remodelling." (PMID 41226477, 2025).
hepatocellular carcinoma (1 paper, 2014). A malignant tumor that arises from hepatocytes. "SLC4A2 (AE2) was found to be upregulated in CRC and hepatocellular carcinoma (HCC) and similar to SLC4A1 appears to interact with p16 in the cytosol." (PMID 24795638, 2014).
Kabuki syndrome (1 paper, 2022). Kabuki syndrome (KS) is a multiple congenital anomaly syndrome characterized by typical facial features, skeletal anomalies, mild to moderate intellectual disability and postnatal growth deficiency. "AD and AR were the most common pattern of inheritance, and the most frequent variant genes were SLC4A1 and KMT2D, which can, respectively, lead to the two most frequent diseases: dRTA (with inclusion of SLC4A1, ATP6V1B1, and ATP6VOA4 genes) and Kabuki syndrome." (PMID 35612621, 2022).
lung adenocarcinoma (1 paper, 2016). A carcinoma that arises from the lung and is characterized by the presence of malignant glandular epithelial cells. "Of the 16 distinguishing proteins, 8 were significantly elevated in lung adenocarcinoma (COPG1, STOML2, HYOU1, PDIA4, EPRS, APEX1, LRPPRC and NANS) whereas 8 proteins were significantly decreased in lung adenocarcinoma (SPTB, SPTA1, ANK1, SLC4A1, HBG1 and HBG2)." (PMID 27799870, 2016).
lupus (1 paper, 2018). "Nineteen probes for 16 lupus-relevant genes (Abca1, Apobec3, Ccr7, Ceacam3, Ets1, Foxp3, Hdac1, Ifng, Irf9, Itgam, Jhdm1d, Mmp9, Oscar, Slc4a1, Tbx21, and Tlr7) were identified from the database of male murine spleen." (PMID 30246031, 2018).
metabolic acidosis (1 paper, 2013). "We admit that SLC4A1 gene was a poor candidate for screening as our patients presented severe metabolic acidosis early in life, but we wanted to exclude the possibility of presenting any mutation in the SLC4A1 gene, as compound heterozygosity has been described." (PMID 24252324, 2013).
migraine (1 paper, 2024). "The MR analysis of eQTL data showed that four drug targets (PROCR, GSTM4, SLC4A1, and TNFRSF10A) were significantly associated with migraine risk in both the FinnGen and UK Biobank cohorts." (PMID 39039470, 2024).
periodontitis (1 paper, 2024). An acute or chronic inflammatory process that affects the tissues that surround and support the teeth. "In this study, SNCA, CA1, SLC4A1, ANK1, and HBB were identified as hub proteins associated with periodontitis progression." (PMID 38802345, 2024). "In addition, specific biological processes and molecular functions during progressive periodontitis were revealed and a set of hub proteins, including SNCA, CA1, HBB, SLC4A1, and ANK1 was strongly associated with the clinical progression status of periodontitis." (PMID 38802345, 2024). "Herein, SNCA, CA1, HBB, SLC4A1, and ANK1, were identified as hub proteins of periodontitis progression." (PMID 38802345, 2024).
potassium deficiency (1 paper, 2023). A condition due to decreased dietary intake of potassium, as in starvation or failure to administer in intravenous solutions, or to gastrointestinal loss in diarrhea, chronic laxative abuse, vomiting, gastric suction, or bowel diversion. "A variant in SLC4A1 giving rise to pseudohypokalaemia was the cause of another patient’s apparent potassium deficiency, resulting in cessation of supplements." (PMID 37946251, 2023).
protein deficiency (1 paper, 2023). "Previous research has shown that erythrocyte membrane protein deficiency caused by pathogenic mutations in the ANK1, SLC4A1, SPTA1, SPTB, and EPB42 genes is the molecular pathogenesis of HS." (PMID 36647015, 2023).
renal fibrosis (1 paper, 2022). A final common manifestation of a wide variety of chronic kidney diseases characterized by glomerulosclerosis and tubulointerstitial fibrosis. "We found that SLC4A1, THY1, and GHR were significantly under-expressed in renal fibrosis, and PLA2G4A and EGR1 were significantly over-expressed compared with the normal group." (PMID 36120336, 2022).
sensorineural hearing loss (1 paper, 2025). "For example, RTA had been reported to be related to the SLC4A1, ATP6V1B1 and ATP6V0A4 genes, and mutations in ATP6V1B1 and ATP6V0A4 genes were predisposed to causing sensorineural hearing loss in children." (PMID 41311422, 2025).
serous ovarian cancer (1 paper, 2025). "The online ROC plotter database demonstrated increased SLC4A1 expression in serous ovarian cancer patients who did not respond to platinum and taxane chemotherapy." (PMID 40565351, 2025).
serous ovarian tumors (1 paper, 2025). "COL12A1, PLEC, and SLC4A1 expression levels were significantly increased in serous ovarian tumors (grade 3) that did not respond to platinum and taxane chemotherapy compared to responders after 6 months of treatment." (PMID 40565351, 2025).
tumor (63 papers, 2006 to 2026). "SLC4A1 plays central roles in pH homeostasis and has been linked to tumor aggressiveness in numerous cancer types." (PMID 27799870, 2016). "Tumor-associated reductions in SPTB were associated with similar reductions in SPTA1 (70%), SLC4A1 (60%), and ANK1 (70%) in tumor tissue when compared to control tissue." (PMID 27799870, 2016). "In their study, samples from three groups (PA, residual PA, and CXPA) were analyzed to identify protein signatures and their results suggested that seven proteins (APOA1, AP1M1, SYCP1, DCD, HBB, HP, and SLC4A1) could be potential signatures for tumor progression or suppression." (PMID 39155517, 2025). "Based on the findings above, this study found EPB42 and SLC4A1 had a strong correlation with PMF, immunofluorescence of EPB42 proved our results in this study, which were detected highly expressed in tumor samples." (PMID 34633991, 2021).
cancer (21 papers, 2011 to 2025). A tumor composed of atypical neoplastic, often pleomorphic cells that invade other tissues. "SLC4A1 predominately expressed in the cytoplasm of cancer cells was significantly increased in all four relapse tissues compared to tissues at diagnosis." (PMID 40565351, 2025). "RNA sequencing data showed decreased SLC4A1 expression in cancers of the lung, colorectal, and breast." (PMID 40565351, 2025). "Lnc- SLC4A1 −1 functions in regulating the NF-κB pathway to mediate the occurrence of diseases such as cancer." (PMID 37265567, 2023). "Expression of the Cr(VI) transporters SLC4A1 andSLC26A1 was tested in a panel of cultured cells derived from typical tissues exposed to asbestosand from asbestos-related cancers." (PMID 36410050, 2022). "Firstly, the mRNA expression levels of most of the SLC4 and SLC26 family members differ widely between normal and cancer tissue, with a clear trend toward upregulation of SLC4A3, SLC4A7, and SLC26A6, and downregulation of SLC4A1 in cancer compared to normal tissue." (PMID 24795638, 2014). "Moreover, whereas in contrast to SLC4A1, SLC4A2 does to some extent localize to the plasma membrane in the cancer cells, it is not clear from the published studies whether the role of the exchanger in cancer progression involves both pHi regulation and p16 sequestration." (PMID 24795638, 2014).
infection (5 papers, 2007 to 2019). The state of being infected such as from the introduction of a foreign agent such as serum, vaccine, antigenic substance or organism. "Five genes in the QTL (Dcaf7, Dusp3, Fam134c, Psme3, and Slc4a1) were significantly differently expressed in a) susceptible vs. resistant mice, and b) humans with S. aureus blood stream infection vs. healthy human subjects." (PMID 24901344, 2014). "At individual gene expression level several transporter genes (Cacna1i, Slc4a1, Slc15a1) and immune response genes (Igsf4d, Ilf1, Csf2) showed no overlap possibly due to infection kinetics." (PMID 17850650, 2007).
SLC4A1 also shares sentences with these, for which no sentence is quoted: anemia (8 papers); Spherocytosis (7); lung carcinoma (4); melanoma (4); Dent disease (3); Hypokalemia (3); sarcoma (3); Sjögren syndrome (3); cardiovascular disease (2); cerebral malaria (2); colon cancer (2); Congenital hemolytic anemia (2); cystic fibrosis (2); erythrocyte disorder (2); erythroleukemia (2); esophageal cancer (2); esophageal squamous cell carcinoma (2); genetic disorder (2); kidney disease (2); paraganglioma (2); renal failure (2); sickle cell anaemia (2); Splenomegaly (2); urolithiasis (2); Acidosis (1); acinar cell pancreatic carcinomas (1); Alkalosis (1); amelogenesis imperfecta (1); autosomal dominant tubulointerstitial kidney disease (1); benign tumor of (1).
A further 71 diseases each share a sentence with SLC4A1 in 1 paper.